ADAM10 (ADAM metallopeptidase domain 10)
Diseases named in the same sentence as ADAM10 in open-access papers (continued):
Sharing a sentence is not in itself a finding about the gene and the disease.
cancer (continued). "In contrast, the repression of Cdkn1a, Cdkn2a, Adam10, Pten and muscle-specific genes in different cancer cell lines or myoblasts cells depends on recruitment of HDAC1, hence, deacetylation of lysine residues in N-terminal tails of histones." (PMID 33731112, 2021). "This idea, however, needs to be addressed with care because of cancer enhancement potentials resulting from a systemic loss of SFRP1 activity, as well as an upregulation of ADAM10 activity." (PMID 32098349, 2020). "Yet, without the implementation of a personalized medicine approach, especially in cancer, ADAM10 inhibition therapy will most likely continue to fail in clinical trials." (PMID 32265938, 2020). "IL-6R was shown to be important in cancer and RA suggesting that ADAM10-mediated cleavage of IL-6R can be targeted for drug discovery for both indications." (PMID 32435655, 2020). "Exosomal ADAM10 was found to be elevated in plasma of cancer patients, and was thought to be an additional pan-cancer marker." (PMID 32265938, 2020). "There has been a significant effort dedicated to the discovery of modulators of ADAM10 activity for multiple indications such as rhematoid arthritis (RA), cancer, immune and neurodegenerative disorders." (PMID 32435655, 2020). "miR-221 and/or miR-222 can attack TIMP-3, inducing drug resistance and facilitating cell growth in different types of cancer through ADAM10- and ADAM17-dependent signaling." (PMID 33419373, 2020). "The authors also found a significant correlation between soluble ULBP-2 serum levels and ADAM10 expression in cancer cells from a cohort of pancreatic ductal adenocarcinoma patients." (PMID 32269567, 2020). "Cell-surface expression levels of MICA significantly increased in response to 5-fluorouracil treatment in hepatocarcinoma and cancer lung cell lines through a mechanism dependent on ADAM10 inhibition." (PMID 32269567, 2020). "In the context of cancer, ADAM-10 and ADAM-17 have been indicated to be the principle proteases for EGFR ligands." (PMID 32948029, 2020). "This review outlines the function of metalloproteinases in platelet biology with a focus on ADAM10 and discusses the role of platelet-derived metalloproteinases in the interaction of platelets with components of the immune system and/or cancer cells." (PMID 32117229, 2020). "MMP-7 and ADAM10 confer antiapoptotic activity to cancer cells by cleaving the Fas ligand from the cell surface." (PMID 33419373, 2020). "The use of ADAM10 expression in plasma or ADAM10 substrates as biomarkers in cancer or for disease progression are extremely promising." (PMID 32265938, 2020). "Among these proteases, ADAM10, whose overexpression has been reported in several cancers, displays numerous features that can be helpful in advancing cancer research." (PMID 30651596, 2019). "Although ADAM10 overexpression was reported in other malignancies, the implication of ADAM10 in proliferation of cancer cells appears to be dependent on the cancer type." (PMID 30651596, 2019). "Previous studies indicate that miR-655-3p is downregulated in several cancers through dysregulation of ADAM10 (a disintegrin and metalloproteinase domain-containing protein 10) and the WNT/β-catenin pathway." (PMID 31122291, 2019). "Supporting our findings, a role of ADAM10 in cell migration/invasion has been reported in several other type of cancers." (PMID 30651596, 2019). "Accumulating evidence has shown that ADAM10 is frequently overexpressed in a variety of cancers, playing an important role in cancer pathogenesis, progression, metastasis and invasion." (PMID 29650964, 2018). "Several ADAM family members, particularly ADAM9, ADAM10, ADAM12, ADAM15 and ADAM17, have been implicated in cancer formation and progression." (PMID 30081852, 2018). "Considering that DSF suppresses migratory properties of various cancer types through targets other than ADAM10, it can be an even more attractive agent." (PMID 29721164, 2018).
cancer (continued). "Following reports in several cancer cell lines, ADAM10 was also found to be overexpressed and to shed mMICA in HCC cells." (PMID 29721164, 2018). "The ADAMs family sheddases, ADAM10 and ADAM17, have been implicated in the proteolytic cleavage of NKG2DL in several types of cancer cells." (PMID 28404876, 2017). "More recently, it has been demonstrated that human CAFs secreted ADAM10-rich exosomes that promoted cell motility and activated RhoA and Notch signaling in several cancer cells." (PMID 28121625, 2017). "MEK inhibition was shown to decrease AXL shedding on cancer cells by inhibiting ADAM10 catalytic activity through the activation of TIMP1, a negative regulator of ADAM10." (PMID 27834845, 2016). "One member of the ADAM family, A disintegrin and metalloproteinase 10 (ADAM10), has been reported to act as a positive regulator of cancer progression in hepatocellular carcinoma, renal cell carcinoma, pancreatic carcinoma, lung cancer and gastric carcinoma." (PMID 25333745, 2015). "Collectively, these data indicate silibinin inhibited HNC tumorigenicity through the activation miR-494-targeting Bmi1 and ADAM10 expression, which resulted in the inhibition of cancer stemness." (PMID 26090866, 2015). "Decreased immunoreactivity of ADAM-10 in cancer cells from regional lymph nodes was correlated with worse prognosis; however this correlation was statistically nonsignificant (P = 0.065)." (PMID 26266086, 2015). "A wide spectrum of protein substrates for ADAM-10 includes molecules that have been shown to be involved in carcinogenesis initiation and cancer progression." (PMID 26266086, 2015). "In the present study, SB suppressed HNC cancer stemness via enhancing miR-494-mediated suppression of Bmi1 and ADAM10." (PMID 26090866, 2015). "Analysis of Kaplan-Meier curves showed that decreased expression of ADAM-10 in cancer cells from regional lymph node metastases was correlated with worse prognosis; however this correlation was statistically nonsignificant (P = 0.065)." (PMID 26266086, 2015). "miR-494-targeting Bmi1 and ADAM10 expression would greatly contribute to a deeper understanding of cancer stemness acquisition in HNC, and promote the development of promising therapeutics for HNC-TICs eradication." (PMID 26090866, 2015). "High soluble CXCL16 (sCXCL16) levels, result of shedding activities like that of ADAM-10, led us to study impact of sCXCL16 on the two cell types with respect to cancer progression." (PMID 25888629, 2015). "Taken together, our results demonstrated a novel miR-494-mediated cancer stemness effect through on the regulation of Bmi1 and ADAM10 expression." (PMID 26090866, 2015). "The expression of ADAM10 is correlated with stemness properties in normal stem cells and cancer stem cells." (PMID 26090866, 2015). "The increased expression of Fat1 in combination with increased levels of the sheddase ADAM10 in clinically relevant cancer patients suggested that soluble Fat1 should be investigated for its utility as a potential serum biomarker." (PMID 24625754, 2014). "Two of the ADAMs, i.e., ADAM10 and 17 appear to promote cancer progression by releasing HER/EGFR ligands." (PMID 21906355, 2011). "The results showed that all these cancer cells expressed ADAM10." (PMID 41178513, 2026). "However, the role of ADAM10 as an APP-cleaving enzyme in response to DHT remains underexplored in cancer." (PMID 41614805, 2025). "Furthermore, activation of Notch signaling mediated by ADAM10 can promote the maintenance of cancer stem cells (CSCs), which are notorious for their resistance to therapy and ability to start metastasis." (PMID 39991567, 2025). "ADAM10, also known as α-secretase, has been implicated in EMT in cancer cells." (PMID 39995975, 2025). "In this context, ADAM10 has emerged as a promising therapeutic goal to treat cancer." (PMID 38667323, 2024). "In cancer, ADAM10 and ADAM17 have been the most actively studied." (PMID 39286024, 2024).
cancer (continued). "Furthermore, xenograft assays with rescue treatments demonstrated the essential role of ADAM10 expression in circSNX5-mediated regulation of in vivo cancer growth." (PMID 39155279, 2024). "Triptolide can reduce the expression of ADAM10 in various cancer cells." (PMID 39457411, 2024). "Furthermore, in this study, AD and its analogs, CD and m62A, inhibit ADAM10 expression in various cancer cells, indicating their anti-cancer potential." (PMID 39211038, 2024). "Nevertheless, regulation of ADAM10 expression by components from Chinese herbal medicines may have potential in cancer progression/tumorigenesis." (PMID 39211038, 2024). "The immunomodulatory role of ADAM10 expression in cancer was subsequently investigated." (PMID 39211038, 2024). "The present study further aimed to determine whether ADAM10 expression is correlated with immunoregulation in pan-cancers." (PMID 39211038, 2024). "There is a known association between ADAM10 (A Disintegrin and Metalloproteinase 10) and the MET receptor, particularly regarding their roles in cellular processes such as signaling, migration, and cancer progression." (PMID 39769452, 2024). "For example, the reduced activity of ADAM10 can result in the accumulation of unprocessed RTKs on the cell surface, thereby enhancing proliferative and survival signals that contribute to cancer progression and resistance to therapies, such as kinase inhibitors." (PMID 39769452, 2024). "Interesting, considering the role of ADAM10 in N-cadherin cleavage and the promigraion effector of N-cadherin in cancers, we proposed the hypothesis that ADAM10/N-cadherin might play a role in MAP4K4 mediated N-cadherin stability." (PMID 36922678, 2023). "The important role of ADAM10 was confirmed by silencing the expression of this protein through genetic engineering methods and, thus, reducing the invasiveness and proliferation capacity of cancer cells." (PMID 37185715, 2023). "Particularly, the role of ADAM10 in cancer is widely discussed." (PMID 36922678, 2023). "Furthermore, Dapagliflozin has previously shown inhibitory effects on different cancer types’ cell adhesion by acting directly on the ADAM10 gene." (PMID 38003585, 2023). "In conclusion, the results of our study indicate that ADAM10 and ADAM17 may be potential biomarkers in cancer linked with DMT2 and CVD as diseases associated with inflammation." (PMID 36286024, 2022). "This makes ADAM17 or ADAM10 an ideal intervention target for the treatment of malignant tumors." (PMID 36606198, 2022). "In addition to the observed anti-apoptotic effects and the stimulation of cell proliferation, proteases like ADAM17 and ADAM10 imprint a cancer stem cell phenotype in cells by shedding of Notch1, and thus support anchorage-independent growth." (PMID 35269560, 2022). "Moreover, ADAM10, once delivered to recipient cancer cells via CAF-derived exosomes, can maintain cancer cell stemness in several tumors via Notch signaling pathway activation." (PMID 36139610, 2022). "These facts, as well as the evidence of overexpression of ADAM10 immature form in CRC, provide further insights into ADAM10 quality control governing ADAM10 trafficking along the secretory pathway with respect to ADAM10 dysregulation in cancer and in tissue homeostasis in general." (PMID 34067041, 2021). "Moreover, the expression of ADAM10 is correlated with the invasive behavior of cancer cells in pancreatic carcinoma and oral squamous cell carcinoma." (PMID 34099061, 2021). "Combination treatment of breast cancer cell lines with Herceptin and ADAM10 knockdown or inhibition potentiates the cancer-inhibiting effect of the antibody, suggesting that such combination therapy might overcome Herceptin resistance in patients." (PMID 34201472, 2021). "In addition, the sheddase ADAM-10 mediates the reduction of NKG2D ligand expression on the cancer cell surface by cleaving MICA/B and is involved in the immune escape mechanism, which impairs NK cell recognition." (PMID 34502547, 2021).
cancer (continued). "ADAM10, as a disintegrin and metalloproteinase 10, participates in multiple catalytic activities, including apoptosis, autoimmunity, cell adhesion and metabolism, cancer proliferation, and metastasis." (PMID 34426753, 2021). "A correlative study using data from the cancer genome atlas found that DLBCLs with a low PD-L1 protein-to-mRNA ratio while also having higher relative expression levels of ADAM10 or ADAM17 had worse overall survival than high PD-L1 protein-to-mRNA counterparts." (PMID 32265938, 2020). "One specific example could be to use the oncolytic virus as a gene therapy vector to deliver small interfering RNA (siRNA) within the cancer cell, knocking down ADAM10 and ADAM17 expression, and thus prevent NKG2DL shedding." (PMID 33352921, 2020). "As DDR1 and ADAM10 consist of a complex in cancer cells, we determined whether unmetabolized dapagliflozin directly increases ADAM10 activity for DDR1." (PMID 31979355, 2020). "ADAM10 is a cell surface enzyme that sheds a wide variety of cell surface proteins with importance in the progression of cancer, inflammation and immune response, suggesting that ADAM10 can be an important target for therapy." (PMID 32435655, 2020). "This incites for an extensive evaluation of ADAM10 agonist effects on cancer." (PMID 32328365, 2020). "Several pieces of evidence show that ADAM10 expression and activity is modulated in the course of cancer progression in an ample variety of tumors, and usually, increased expression levels of this protease correlate with cancer progression." (PMID 32269567, 2020). "However, SFRP1′s modulation of ADAM10 and Wnt signaling has a flip side, which includes the promotion of cancer and the negation of other beneficial aspects." (PMID 32098349, 2020). "Although ADAM17 SMIs show anti‐cancer efficacy in numerous preclinical models, these inhibitors are highly toxic due to the non‐specific targeting of other metalloproteinases (e.g., ADAM10), thus highlighting the need for highly selective ADAM17 inhibitors with an alternate mode of action." (PMID 30833304, 2019). "We hypothesized that degradation of VE-cadherin through ADAM10 is a relevant mechanism contributing to the invasiveness of cancer cells that might be modulated by ionizing irradiation." (PMID 31619190, 2019). "Also, CAFs were found to secrete ADAM10-rich exosomes to promote cell motility and activate RhoA and Notch signaling in several cancer cell lines." (PMID 30227608, 2018). "This investigation, however, must consider the various other ADAM10 substrates, because although its activation would result in beneficial outputs for AD patients, it can result in dangerous triggers for other diseases, such as cancer." (PMID 29382156, 2018). "Our data describing ADAM10 inhibition has uncovered another aspect of DSF as an anti-cancer agent." (PMID 29721164, 2018). "Therefore, DSF was suggested to enhance mMICA levels and suppress sMICA production with enzymatic inhibition of ADAM10, leading to anti-cancer activity of NK cells." (PMID 29721164, 2018). "Notably, ADAM10 and ADAM17 mutations are associated with many diseases in humans, including a variety of cancers." (PMID 28068334, 2017). "Therefore, PAX2 seems to play an important role in ADAM10 expression control—at least in cancer cells." (PMID 28367112, 2017). "The extracellular domain of HER2 is shed by protease-like ADAM10 in cancer cells." (PMID 26657506, 2016). "For these reasons, ADAM10 has been proposed as a target for anti-cancer therapy, in particular its functional inhibition might be efficacious in reducing activation of EGF-receptors." (PMID 27517630, 2016). "Our study was entirely focused on ADAM10 expression in cancer metastases from regional lymph nodes." (PMID 26266086, 2015). "ADAM10-mediated proteolytic cleavage of substrate proteins is considered to be involved in the pathophysiology of multiple life-threatening diseases, including cancer." (PMID 25333745, 2015).
cancer (continued). "Interestingly, lower ADAM-10 expression in cancer cells from nodal metastases was also correlated with older age at diagnosis (P = 0.037)." (PMID 26266086, 2015). "Thus, ADAM10 is a potential therapeutic target for anti-cancer treatments." (PMID 39211038, 2024). "However, in cancer, alterations in ADAM10 activity can lead to dysregulated signaling." (PMID 39769452, 2024). "Therefore, further studies are needed to research the specific role of ADAM10 in each pan-cancer." (PMID 39346916, 2024). "From the combination of elevated PrP levels and increased ADAM10 expression/activity found in various cancer types, one can anticipate that sPrP, the product likely generated by this molecular encounter, may be mechanistically involved in certain oncogenic processes." (PMID 35084572, 2023). "However, given that ADAM10 has multiple substrates, it is essential to emphasize that although ADAM10 overactivation would result in beneficial effects for AD, it can be detrimental to other diseases, such as cancer." (PMID 36674432, 2023). "In the light of our results, ADAM10 inhibition may present a complementary strategy to block the ADAM10 –E-cadherin–EGFR family member axis and thereby not only execute anti-HCV activity but also reduce the risk of cancer development in chronic HCV patients." (PMID 37967063, 2023). "In our opinion, ADAM10 could play an important role in the very early stages of cancer." (PMID 36286024, 2022). "The seven prevalent ‘candidate genes’ (ADAM10, ADAM17, AKT1, CTNNB1, ESR1, FGFR1, PIK3CA) showed direct associations with enriched terms under the categories of ‘Neurodegenerative disorders’, ‘Neurodevelopmental diseases’, ‘CNS tumour/cancer’ and ‘Cellular Signaling pathways’." (PMID 36229517, 2022). "However, ADAM10 is also elevated broadly in many cancers on exosomes." (PMID 32265938, 2020). "GI254023X, blocking ADAM10 catalytic activity, drastically reduced MPM cell migration and invasion indicating that ADAM10-related molecular mechanisms underlying the regulation of MPM cancer cell migration and invasion are dependent on the metalloprotease domain activity." (PMID 30651596, 2019). "Therefore, PAX2 appears to play an important role in ADAM10 expression, at least in cancer cells." (PMID 29382156, 2018). "The increase of the ADAM10-immature isoform expression is likely to be immunogenic and to contribute to the reduction of net ADAM10 activity, which is a beneficial condition that may be instrumental in the limitation of cancer progression." (PMID 27517630, 2016). "The detail role of ADAM10 in regulating cancer stemness in HNC-TICs may need further investigation." (PMID 26090866, 2015). "Similarly, epirubicin, a chemotherapeutic drug known to down-regulate ADAM10 expression in cancer cells, when used in combination with CDX-011, could potentially enhance its efficacy." (PMID 20711474, 2010). "Predicted matching epitopes included various cancer antigens, including FOXM1 (IYTWIEDHF), mucin 1 (LLLLTVLTV), Cancer/testis antigen 1 (AMPFATPMEA, GAARASGPGGGAPRG) and ADAM10 (GQYGNPLNK)." (PMID 40211048, 2025). "Given the important role that ADAM10 plays in both pan-cancer and HCC, we further analyzed the prognostic value of ADAM10 in both pan-cancer and HCC by single-factor Cox regression analysis and log-rank test." (PMID 39346916, 2024). "In the context of cancer, the shedding of MET by ADAM10 can affect tumor progression by altering how cells respond to growth factors and their surrounding environment." (PMID 39769452, 2024). "Both AD and CD inhibited LAG3 expression in vitro, indicating the possible pathways of AD/ADAM10/LAG3 or CD/ADAM10/LAG3 in anti-cancers, or suggesting a potential method for immunotherapy of cancers." (PMID 39211038, 2024).